NLRP1 (NLR family pyrin domain containing 1)
Diseases named in the same sentence as NLRP1 in open-access papers (continued):
Sharing a sentence is not in itself a finding about the gene and the disease.
COVID-19 (17 papers, 2020 to 2025). A disease caused by infection with severe acute respiratory syndrome coronavirus 2. "Considering the evidence together, it is possible that decreased DPP9 expression in the lungs can predispose patients with COVID-19 to develop lung injury mediated by increased NLRP1-dependent pyroptosis." (PMID 34027315, 2021). "Receiver operating characteristic curve indicated that NLRP1 might be a potential diagnostic biomarker for the death of COVID-19 patients." (PMID 36343035, 2022). "Serum NLRP1 also exhibited diagnostic value for the death of COVID-19 patients." (PMID 36343035, 2022). "The diagnostic value of serum NLRP1 for the death of patients with COVID-19 was analyzed." (PMID 36343035, 2022). "Besides, we for the first-time revealed serum NLRP1 might serve as a promising diagnostic biomarker for the death of COVID-19 patients, and those with lower NLRP1 had longer survival time." (PMID 36343035, 2022). "In this sense, only one work has described a difference of rs12150220 NLRP1 between severe and mild Brazilian COVID-19 patients." (PMID 38612539, 2024). "In this study, the expression of NLRP1, NLRP3, and ASC and their association with serum level of IL-1β were explored in COVID-19 patients." (PMID 37723427, 2023). "This study aimed to evaluate the expression of NLR family pyrin domain containing 1 (NLRP1), NLRP3, and Apoptosis-associated speck-like protein containing a CARD (ASC) as well as their association with serum level of interleukin (IL)-1β in patients with coronavirus disease 2019 (COVID-19)." (PMID 37723427, 2023). "A positive correlation was found among NLRP1 and inflammatory factors, and COVID-19 patients with lower NLRP1 had longer survival time." (PMID 36343035, 2022). "We suspect that lower DPP9 may exacerbate pathogenesis of IPF and COVID-19 by preventing excess NLRP1-mediated inflammation and weakening cell-to-cell adhesion, promoting a dysregulated cycle of inflammation and fibrosis." (PMID 39876559, 2025). "Given the growing body of evidence linking dysregulated immune responses and cytokine storm to severe COVID-19 outcomes, investigating the gene expression of NLRP1, NLRP3, and ASC, as well as the serum levels of IL-1β, in patients with COVID-19 is of paramount importance." (PMID 37723427, 2023). "This study might provide clinical evidence for the effect of TEN on NLRP1, inflammation and prognosis for COVID-19 patients in ICU." (PMID 36343035, 2022). "Finally, the deep investigation is needed for the molecular mechanism of NLRP1 in COVID-19 patients." (PMID 36343035, 2022). "Besides, NLRP1 exhibited valuable potential for the diagnosis of the death of COVID-19 patients, and those with higher NLRP1 had shorter survival time." (PMID 36343035, 2022). "This study might bring more clinical evidences for the use of TEN and the effect of NLRP1 on COVID-19 patients in ICU." (PMID 36343035, 2022). "Global statistical analysis could not confirm the association with COVID-19 negative status but it showed a trend for NLRP1 although it not statistically significant (p = 0.093)." (PMID 36228008, 2022). "Furthermore, NLRP1-dependent pyroptosis is sufficient to cause progressive lung injury, independent of NLRP3 activation or IL-1b secretion, which suggests a relevant role of DPP9 in mediating lung injury seen in severe COVID-19." (PMID 34027315, 2021). "From day 0 to day 7, a significant induction of the inflammasome pathway genes, which included NLRC4, NLRP1, CASP1, PYCARD, and IL-18, was detected in COVID-19+ individuals compared to healthy controls." (PMID 38543837, 2024). "The upregulation of NLRP1 and ASC in blood samples from COVID-19 cases suggests a potential role for these inflammasome components in the immune response to SARS-CoV-2 infection." (PMID 37723427, 2023). "Similar to the mDC subsets, the NLRP1, AIM2, NAIP expression was also highly activated pDCs from the in COVID-19 groups." (PMID 36439166, 2022).
COVID-19 (continued). "The fourth set of modules involved ribosomal proteins and inflammasome function (top genes by membership included NLRP1, MAP3K14, and FOXP1) and was negatively correlated with COVID-19 severity in monocytes." (PMID 35216673, 2022). "In particular, NLRP3 and NLRP1 inflammasome activation—as well as the components of its signaling, i.e., CASP1, IL-1β, and IL-18, etc.—show a relationship with the inflammatory factors and disease progression in patients with COVID-19." (PMID 38612539, 2024). "Additionally, the distribution of the haplotypes of NLRP3, NLRC4, NLRP1, CARD8, CASP1, IL1B, and ATG16L1, with a frequency greater than 5% in HC, were similar between COVID-19 patients with mild, moderate, severe, and critical infection, and HC." (PMID 38612539, 2024). "NLRP1 and ASC may have a more critical role in the generation of the active form of IL-1β in COVID-19 patients compared to NLRP3." (PMID 37723427, 2023). "Therefore, it is highly possible that viral dsRNA activates NLRP1 by binding to it through a leucine-rich repeat domain of NLRP1 and participates together with NLRP3 to the over-responses of the immune system leading to COVID-19 severe symptoms." (PMID 37360532, 2023). "mRNA expression of ASC (P = 0.008) and NLRP1 (P = 0.03) gene had a significant increase in COVID-19 patients compared to HS, while there was no significant increase in the expression of NLRP3 between the studied group." (PMID 37723427, 2023). "Additionally, the ASC and NLRP1 gene expression were increased significantly in COVID-19 patients compared to HS, whereas there was no significant increase in the expression of NLRP3 between the investigated group." (PMID 37723427, 2023). "Furthermore, our DEG analysis of scRNA-seq of bronchoalveolar fluid of patients with COVID-19 showed that expression of DPP9, NLRP1, and GSDMD, an effector protein for pyroptosis, was significantly altered in Mo/Mφs of patients with severe COVID-19 compared to their moderate counterparts." (PMID 34027315, 2021). "Furthermore, S6 and S7 cells highly expressed pyroptotic genes (such as NLRC4/5, NLRP1/12 and CASP1) in both KD and severe COVID-19 patients (data not shown)." (PMID 36159873, 2022).
Cognitive impairment (15 papers, 2011 to 2024). Abnormal cognition is characterized by deficits in thinking, reasoning, or remembering. "In this study we have shown for the first time an age-related heightened activation of the NLRP1 inflammasome system associated with increased inflammation and cognitive impairment in the hippocampus of aged rats." (PMID 22133203, 2011). "Aging leads to significant cognitive impairment in hippocampal dependent spatial learning tasks that may be associated with increased inflammatory cytokine production resulting from NLRP1 activation." (PMID 22133203, 2011). "The use of aspirin and NLRP1 siRNA significantly attenuated METH-induced cognitive deficits while decreasing the activities of NLRP1 and cleaved caspase-1, IL-1β, and TNF-α, providing further evidence of complex programmed cell death mechanisms." (PMID 39224601, 2024). "In a study involving METH abuse in rats, elevated NLRP1 activity was observed in the hippocampus, and NLRP1 inhibition significantly ameliorated METH-induced cognitive impairment." (PMID 39224601, 2024). "In the APP/PS1 AD mice model, NLRP1 is upregulated and NLRP1 silencing in this AD model reduces neuronal pyroptosis and cognitive impairment." (PMID 37251647, 2023). "For example, schisandrin (SCH), as a lignan representing Schisandra chinensis, inhibits the action of the NLRP1 inflammasome on neuronal pyroptosis in AD mice, thereby alleviating cognitive impairment." (PMID 36713841, 2023). "In APP/PS1 mice, the simultaneous silencing of NLRP1 and caspase-1 reduced neuronal cell death in the cortex and hippocampus, and improved cognitive impairment." (PMID 37921870, 2023). "In contrast, suppressing NLRP1 in APPswe/PS1dE9 mice brought out a significantly reduction in the amount of neuronal pyroptosis as well as cognitive impairment." (PMID 36713841, 2023). "The implication of the Nlrp1-Casp1-Casp6 neurodegenerative pathway in cognitive impairment was demonstrated in the APPSwedish/Indiana (APPSw/Ind) transgenic J20 AD mouse model." (PMID 36220815, 2022). "Reversal of cognitive deficits with VX-765 is likely due to reversal of neuronal degeneration, which is induced via the Nlrp1 inflammasome-Casp1-Casp6 neurodegenerative pathway." (PMID 36220815, 2022). "In addition, manifestations of cognitive impairment and changes in the NLRP1/Caspase1/GSDMD signaling pathway were found in an in vivo model of METH administration in rats." (PMID 39224601, 2024). "While the NLRP1 inflammasome mainly exists in neurons, studies have shown that it plays an important role in the pathology of neuronal damage and disturbance of consciousness as well as cognitive impairment, a major feature of people with depression." (PMID 36556951, 2022). "In the APPswe/PS1dE9 mouse model of AD, neuronal NLRP1 activation was reported, while neuronal pyroptosis and cognitive impairments could be reduced with siRNA (small interfering RNA) to knockdown NLRP1." (PMID 32635451, 2020). "Consequently, Nlrp1, Casp1, and Casp6 represent feasible therapeutic targets against age-dependent cognitive deficits and AD." (PMID 30254377, 2018). "Thus, it appears that heightened NLRP1 inflammasome activity is induced by the natural aging process resulting in increased inflammatory cytokine production and cognitive impairment that can be attenuated by inhibition of inflammasome activation." (PMID 22133203, 2011). "Inhibition of NLRP1 expression could ameliorate age-related cognitive deficits." (PMID 37055801, 2023). "Our recent work has shown that the NLRP1 inflammasome in neurons plays a crucial role in the innate CNS immune response induced by injury, but whether the NLRP1 inflammasome contributes to inflammatory cytokine production and cognitive impairment due to aging remains largely undefined." (PMID 22133203, 2011). "An in vivo knockdown of NLRP1 or (pro)caspase-1 in B6C3-Tg mouse brains significantly decreased neurons’ pyroptosis and mitigated cognitive impairment." (PMID 33261147, 2020).
Cognitive impairment (continued). "Studies showed NLRP1 expression was up-regulated in the brain tissue of APP/PS1 mice, however, using NLRP1 inhibitor decreased caspase-1 and IL-1β expression, reduced neuron pyroptosis, and finally improved cognitive impairment." (PMID 35782390, 2022). "It is more likely that a reversible type of degeneration, defined by loss of neuronal structure or function in the absence of cell death, and induced via the neuronal Nlrp1-Casp1-Casp6 pathway is responsible for cognitive deficits in J20." (PMID 36220815, 2022). "However, our findings do not entirely support microglia as a pivotal player in Nlrp1-Casp1-Casp6-mediated cognitive impairment." (PMID 36220815, 2022). "Chinese herbal compound Naofucong has been mainly used to treat cognitive disorders in Traditional Chinese Medicine The present study aimed to investigate whether its neuroprotective effects might be related to the inhibition of P2X7R/NLRP1/caspase-1 mediated neuronal injury or not." (PMID 34093185, 2021).
skin cancer (15 papers, 2017 to 2026). "Germline gain-of-function mutations in NLRP1 cause inflammatory skin syndromes and predispose patients to the development of cutaneous squamous cell carcinomas (cSCCs), a major type of skin cancer originating from keratinocytes." (PMID 40593496, 2025). "This is an interesting association of NLRP1 and skin cancer, reinforced by the fact that the NLRP1 agonist, UVB irradiation, is a primary risk factor for keratinocyte carcinomas." (PMID 33925158, 2021). "NLRP1 is the most highly expressed inflammasome in human skin, and gain-of-function NLRP1 mutations cause chronic skin inflammation and skin cancer." (PMID 33584697, 2020). "In human, gain-of-function mutations of the NLRP1 gene cause syndromes mediated by inflammasome activation in keratinocytes that are characterised by skin inflammation and skin cancer susceptibility." (PMID 29348630, 2018). "A recent study unveils a very exciting finding about genetic mutations of the NLRP1 inflammasome in some skin cancers." (PMID 28955343, 2017). "Elegant research work from Reversade’s lab establishes a connection between genetic mutations of NLRP1 gene and increased susceptibility to skin cancer in human patients." (PMID 28955343, 2017). "Functional studies of these mutations reveal that gain-of-function mutations in NLRP1 increase susceptibility to skin cancer, and a unique regulatory auto-inhibition mechanism in the NLRP1 inflammasome." (PMID 28955343, 2017). "Together, these studies demonstrate that germline, gain-of-function NLRP1 mutations cause skin cancer and skin disorders." (PMID 28955343, 2017). "NLRP1 inflammasomes have become a focal point in skin biology as mutations in NLRP1 contribute to the genetic basis of dermatological diseases and heighten the risk of skin cancer." (PMID 42222687, 2026). "Studies have found that NLRP1 inflammasomes have taken centre stage in skin biology, as mutations in NLRP1 underlie the genetic etiology of dermatological diseases and increase the susceptibility to skin cancer." (PMID 38217019, 2024). "Moreover, gain-of-function mutations of NLRP1 cause inflammatory skin syndromes and a predisposition for the development of skin cancer." (PMID 32640751, 2020). "However, given its role in inflammasome activation, it is plausible that silencing NLRP1 might also reduce inflammation and thereby the risk of skin cancer." (PMID 39839625, 2024). "What is more, in the skin, NLRP1 is highly expressed in keratinocytes, the primary cell type involved in other skin cancer – basal cell carcinoma (BCC)." (PMID 39839625, 2024). "MSPC predisposes patients to the development of SCCs (squamous cell carcinomas), a major type of skin cancer, suggesting that NLRP1-dependent skin inflammation supports the development of tumors." (PMID 32640751, 2020). "However, expression of NLRP1 is strongly reduced in cSCCs suggesting a complex role of the NLRP1 inflammasome in the development of this type of skin cancer." (PMID 40593496, 2025). "Similarly, UVB induces inflammation (sunburn), which is likely mediated by NLRP1 inflammasome activation in keratinocytes, as well as the development of skin cancer." (PMID 36293159, 2022). "However, the role of NLRP1 in skin cancer seems to be more complex because expression of the NLRP1 inflammasome and of proIL-1β is suppressed in human SCC cell lines and tumor biopsies." (PMID 36581625, 2022). "The finding that expression of the NLRP1 inflammasome, although GoF mutants of NLRP1 predispose for SCC development, is suppressed in SCC cell lines and existing SCC tumors supports a dual, paradoxical and cell type, stage- and/or time-specific role of inflammasomes in (skin) cancer development." (PMID 32640751, 2020). "Furthermore, as the NLRP1 pathway is silenced in skin cancer, pharmacological activation of NLRP1 in affected skin lesions, for example by talabostat, might represent a successful approach for the treatment of skin cancer patients." (PMID 32640751, 2020).
skin cancer (continued). "In summary, we identify p62 as a novel negative regulator of the NLRP1 inflammasome in human cutaneous SCC cells, in which suppression of NLRP1 by increased levels of p62 supports stress resistance of skin cancer cells." (PMID 36581625, 2022).
colitis (14 papers, 2017 to 2024). Inflammation of the colon. "The NLRP1 inflammasome also plays a protective role in the development of colitis-associated CRC, which is associated with the release of the effector cytokines IL-1β and IL-18." (PMID 39684769, 2024). "Inversely, some other researches pointed that NLRP1 inflammasome decreased colitis and colitis‐associated tumorigenesis." (PMID 35574984, 2022). "To confirm the pathogenic role of NLRP1 activation during DSS-induced colitis, we utilized a mouse model that displays hyper-activated Nlrp1a." (PMID 30214011, 2018). "We have shown that loss of the Nlrp1 inflammasome ameliorates DSS-induced colitis by promoting expansion of beneficial gut microbes belonging to the Clostridiales phylum, with concomitant increased butyrate production in the colon." (PMID 30214011, 2018). "Given these links between IBD and NLRP1, we use the model of DSS-induced colitis in mice that are deficient for all three paralogs of Nlrp1 (Nlrp1−/−) and find that they are protected from severe disease pathology." (PMID 30214011, 2018). "The colitis-protective effects of Nlrp1 deficiency are thus reversed by vancomycin treatment, but recapitulated with butyrate supplementation in wild-type mice." (PMID 30214011, 2018). "This shows that IL-18 signaling after Nlrp1 activation increases the disease severity of DSS-colitis, associated with increased IFNγ-producing Th1 cells." (PMID 30214011, 2018). "Inversely, other authors demonstrated that NLRP1 attenuates colitis and colitis-associated tumorigenesis." (PMID 29214170, 2017). "NLRP1 inflammasome attenuates colitis and colitis-associated tumorigenesis." (PMID 34257569, 2021). "Moreover, an activating mutation of NLRP1 aggravated DSS-induced colitis, which was associated with an enhanced Th1 response and an increased IL-18/ IFNγ production in the gut." (PMID 33808793, 2021). "As an initial test to see if the DSS-colitis phenotype of Nlrp1-deficient mice was related to a commensal imbalance, we performed 16S ribosomal RNA sequencing on stool from littermates of Nlrp1+/− matings, which had been housed individually for 6 weeks after weaning." (PMID 30214011, 2018). "Moreover, we demonstrate that increased IL-18 is associated with an increased Th1 response during DSS-induced colitis, while loss of Nlrp1 prevents this, and leads to increased butyrate-producing commensals from the Clostridiales order." (PMID 30214011, 2018). "Moreover, recent findings have shown that NLRP1 could protect against metabolic syndrome as well as colitis-associated tumorigenesis, which indicates that NLRP1 possibly acts as a homeostatic factor." (PMID 31396539, 2019). "It has been found that NLRP1−/− mice had significantly increased gastrointestinal inflammation and tumorigenesis compared with wild-type mice, indicating that NLRP1 has a protective role in reducing colitis and colitis-related CRC." (PMID 39062587, 2024). "NLRP1 activation can exacerbate DSS-induced colitis, relating to enhanced Th1 response and increased IL-18/IFNγ production in the intestine." (PMID 38455052, 2024). "The latest research shows that secoisolariciresinol diglucoside alleviates colitis by inhibiting NLRP1 inflammasomes, correlating with reduced IL-1β, IL-18, and TNF-α levels in DSS-induced colitis mice." (PMID 38455052, 2024). "Reports indicate that NLRP1 exacerbates colitis through interactions with symbiotic microorganisms in animal models of IBD." (PMID 38455052, 2024). "Further studies demonstrated that the colitis in mice carrying activated Nlrp1 was dependent on IL-18." (PMID 33808793, 2021). "Mice deficient in Nlrp1 display an increased abundance of butyrate‐producing bacteria of the order Clostridiales, which protects against DSS‐induced colitis." (PMID 34705319, 2021). "In an animal model of IBD, it has been reported that NLRP1 exacerbates colitis through the interaction with commensal microbes." (PMID 34705319, 2021).